IRF7 (interferon regulatory factor 7)
Diseases named in the same sentence as IRF7 in open-access papers (continued):
Sharing a sentence is not in itself a finding about the gene and the disease.
Sepsis (continued). "Knockdown of Irf7 or Srg3 significantly alleviated the symptoms of sepsis-induced lung injury and reduced M1 macrophage polarization in rat lung tissue." (PMID 37946128, 2023). "In previous experiments, we confirmed that Irf7 can activate the expression of Srg3 by transcription, and that inhibiting Irf7 can significantly improve lung injury in rats with sepsis." (PMID 37946128, 2023). "The findings of this study suggest that IRF7 might be a therapeutic target for improving cell-autonomous defenses to replace the antibiotics used in sepsis treatment." (PMID 41212050, 2025). "The results suggested that IRF7 was stimulated to defend against sepsis." (PMID 41212050, 2025). "IRF7 is required for macrophage-mediated bacterial killing during sepsis." (PMID 41212050, 2025). "In sum, these results suggest that IRF7 drives macrophages to protect against sepsis." (PMID 41212050, 2025). "In sum, inducing IRF7 expression via rAAV9-Irf7 might promote the autophagic clearance of pathogens to improve sepsis outcomes." (PMID 41212050, 2025). "Notably, IRF7’s functional role in sepsis remains unresolved, with reports indicating protection or detriment." (PMID 41212050, 2025). "In sum, these results suggest that IRF7 is a regulator of autophagy in macrophages during sepsis." (PMID 41212050, 2025). "Taken together, these data suggest that IRF7 defends against polymicrobial sepsis via autophagy." (PMID 41212050, 2025). "IRF7 is involved in the autophagic response of macrophages during sepsis." (PMID 41212050, 2025). "Given that IRF7’s upregulation pattern precisely coincides with the autophagic flux window during the middle-late stage of sepsis, we hypothesized that IRF7 programs autophagy to control disease outcomes." (PMID 41212050, 2025). "Next, to determine whether IRF7 is a target for treating sepsis, we intravenously administrated rAAV9-Irf7 to WT mice." (PMID 41212050, 2025). "To determine whether the ability of IRF7 to defend against polymicrobial sepsis is dependent on autophagy, we treated mice that underwent CLP with either BECN1 or Wort." (PMID 41212050, 2025). "A recent study found that IRF7 is involved in the progression of sepsis associated LI by regulating Srg3 and ferroptosis, but there are no reports on the mechanism of IRF7 in SAP." (PMID 38671352, 2024). "If Ppargc1a/b activation by IRF-7 translates to the clinical setting, it should be possible to establish whether this pathway protects metabolic and organ function during sepsis." (PMID 21966468, 2011). "We found that IRF7 might be stimulated by the IFN-β/JAK1/STAT3 pathway in polymicrobial sepsis." (PMID 41212050, 2025). "Moreover, the role of interferon regulatory factor 7 (IRF7) in sepsis has been debated." (PMID 41212050, 2025). "Thus, we next focused on determining if IRF7 is required for bacterial clearance during sepsis." (PMID 41212050, 2025). "Furthermore, IRF7 drove macrophages to protect against sepsis." (PMID 41212050, 2025). "In summary, Irf7 can activate the expression of Srg3 by transcription, thereby increasing the activity of the NF-κB signaling pathway, activating ferroptosis in lung epithelial cells, promoting M1 macrophage polarization, and exacerbating the symptoms of acute lung injury in sepsis." (PMID 37946128, 2023). "Thus, timed interventions to manipulate IRF-7 may improve cell protection and hasten the resolution of multiple organ failure in patients with sepsis and mitochondrial dysfunction." (PMID 21966468, 2011). "Anyway, IFN-β is not an ideal agonist for stimulating IRF7 to protect mice from polymicrobial sepsis." (PMID 41212050, 2025). "Unlike the effects of IRF3 on sepsis, our study revealed that IRF7 was activated to clear bacteria and ultimately reduced the death rate of septic mice." (PMID 41212050, 2025).
Sepsis (continued). "In this study, WT mice were injected with rAAV9-Irf7, and the results showed that IRF7 overexpression promoted the autophagic clearance of pathogens and improved sepsis outcomes, establishing its potential as a nonantibiotic therapy." (PMID 41212050, 2025). "IRF7 overexpression might be a nonantibiotic therapy for sepsis." (PMID 41212050, 2025). "Moreover, Irf7 deficiency did not inhibit Ifna or Ifnb expression, suggesting that type I IFN responses are not the IRF7-driven determinants of peritoneal macrophage-mediated sepsis improvement." (PMID 41212050, 2025). "Using TLR3 agonist PolyI:C to induce IRF-7 in TLR2−/− mice, we found no increase in basal Ppargc1a mRNA levels, but we did rescue the Ppargc1a response in sepsis." (PMID 21966468, 2011).
type 1 diabetes (10 papers, 2012 to 2024). "IRF7 has been identified as the key driver of an inflammatory network associated to type 1 diabetes, which greatly overlaps with the IFN network found in the present study." (PMID 25938420, 2015). "Also, an IRF7-dependent inflammatory network was associated with the pathogenesis of type I diabetes and infection induced Irf7 in endothelial cells may contribute to the development of vascular lesions." (PMID 22776377, 2012). "Four SNPs with a strong type 1 diabetes association and an eQTL signal were seen in ADAR (encoding RNA-specific adenosine deaminase), IL1R1 (encoding IL-1 receptor type 1), IRF7 (encoding IFN regulator 7) and the OAS gene family." (PMID 33973017, 2021). "Here, we focus on the multi-tissue eQTL mapping of a previously reported Interferon regulatory factor 7 IRF7-driven inflammatory network (IDIN) found to be associated with immune response and increased risk of type 1 diabetes in humans (Heinig etal., 2010)." (PMID 26504141, 2016). "IRF7 expression was decreased by 17% in autoantibody-positive individuals (p = 6.10 × 10−3, 95% CI 0.02, 0.14); the expression of this gene was increased in longstanding type 1 diabetes by 14% (p = 4.00 × 10−2, 95% CI −0.11, −0.002)." (PMID 33973017, 2021). "An interferon regulatory factor 7-driven inflammatory network (IDIN) enriched for viral response genes has been identified in the BB rat, and genes from the analogous human IDIN have been shown to associate with susceptibility to type 1 diabetes." (PMID 24147110, 2013). "For example, IRF7 (the interferon regulatory factor 7) driven regulatory cascade in which genetic variation on chromosome 15q25 leads to type 1 diabetes (pathway: 04940) and XBP1 (X-box binding protein 1) induce pancreatic beta cell dysfunction and apoptosis of type 1 diabetes." (PMID 26688819, 2015).
cardiac hypertrophy (9 papers, 2015 to 2025). "Meanwhile, IRF7 mitigates pathological cardiac hypertrophy and fibrosis caused by pressure overload by inhibiting the NF-κB signaling pathway." (PMID 41300325, 2025). "Cardiac specific IRF7 overexpression attenuated pressure overload-induced hypertrophy, fibrosis, and dysfunction, whereas IRF7 knockout augmented cardiac hypertrophy and fibrosis." (PMID 38665231, 2024). "A possible reason is that the role of IRF7 in cardiac hypertrophy is a combination of its function in both cardiomyocytes and non-cardiomyocytes in the heart." (PMID 34790705, 2021). "The genes that were most highly expressed in only a single-cell type were Gm20658 (fibroblasts), Ucp3 (cardiomyocytes), Spock2 (endocardial cells), Irf7 (endothelial cells), and Ifi206 (macrophages), of which Ucp3 and Irf7 were involved in heart failure and pathological cardiac hypertrophy." (PMID 37010266, 2023). "Unlike in DM models, Irf7 gene expression showed no significant alterations after angiotensin II (AngII)-induced HF, and heart-specific overexpression of Irf7 significantly attenuated pressure overload–induced cardiac hypertrophy, fibrosis, and dysfunction." (PMID 40369551, 2025).
diabetes (9 papers, 2008 to 2025). "In our analysis of all sequenced tissues, we found that dysregulation of Irf7, a master regulator of the interferon response, is the major driver of the development of diabetes." (PMID 37979047, 2024). "In diabetes, IRF7 knockdown increases anti-inflammatory IL-10 production and decreases proinflammatory IL-6 level in bone marrow-derived macrophages." (PMID 36336986, 2023).
Autoimmunity (7 papers, 2013 to 2025). The occurrence of an immune reaction against the organism's own cells or tissues. "In this review, we provide a comprehensive overview on the current knowledge of the role of IRF7 in immunity and autoimmunity." (PMID 37638030, 2023). "We also discuss the latest relevant research in autoimmunity and oncogenesis toward understanding IRF7 beyond its role in immunity." (PMID 37638030, 2023). "In addition to antiviral immunity, we also discuss the role and mechanism of IRF7 in autoimmunity, and the further research will expand our understanding of IRF7." (PMID 37638030, 2023). "Studies with silica-induced lung inflammation, while only indirectly implying mechanisms of silica-induced autoimmunity, suggest that, like idiopathic lupus and pristane-induced autoimmunity, innate mechanisms involving IRF7 and type I IFN might play pivotal roles." (PMID 23557436, 2013). "On the other hand, the role and mechanisms of IRF7 in IFN-III and autoimmunity remain to be explored." (PMID 37638030, 2023). "Our study further reveals that transcriptional regulators such as IRF3, IRF7, STAT1, and MYB are critically involved in T cell-mediated autoimmunity, along with ncRNAs LINC00487, LINC01260, and MIR223 with their expression patterns linked to immune dysregulation." (PMID 39844998, 2025).
colon carcinoma (7 papers, 2021 to 2025). "pDC exhaustion may also be tumor- and even stage-specific, as recently shown in colon cancer where the presence of activated pDCs, as assessed by nuclear localization of IRF7, associated with increased patient survival." (PMID 38504978, 2024). "Our data have demonstrated that IFNγ enhanced IRF3/7 expression and upregulation of IRF7 increases the expression of IFI35 in both murine colon cancer cells." (PMID 37380972, 2023). "Importantly, the overexpression of IRF7 significantly increased the expression of IFI35 in both murine colon cancer cell lines." (PMID 37380972, 2023). "Thus, IRF7 was a unique transcription factor that was stimulated by IFNγ and drove the expression of IFI35 in both murine colon cancer cell lines." (PMID 37380972, 2023).
Immunodeficiency (6 papers, 2009 to 2025). Failure of the immune system to protect the body adequately from infection, due to the absence or insufficiency of some component process or substance. "ITGB2 plays a vital role in immune response, silencing ITGB2 leads to leukocyte adhesion deficiency and IRF7 is associated with immunodeficiency, enhanced expression of ACSS3 will help the migrated cells to evade from the immune elimination." (PMID 35685372, 2022). "Age‐related immune dysfunction stemmed from impaired IRF7 signaling and defective SNARE‐mediated cytokine secretion in CD11b+ cells." (PMID 40583123, 2025). "We found multiple genes with ClinVar variants from patients with primary immune deficiencies (for example, IRF9, IRF7, STAT1, STAT2) that are not GWAS-linked genes but are in their network vicinity, providing evidence of the importance of this gene module for these diseases." (PMID 36823319, 2023).
psoriasis (6 papers, 2020 to 2025). An autoimmune condition characterized by red, well-delineated plaques with silvery scales that are usually on the extensor surfaces and scalp. "In this model, topical imiquimod administration results in a local psoriasis-like skin inflammation driven by nuclear factor kappa B (NFƙB) and interferon regulatory factor 7 (IRF7) pathways." (PMID 38748319, 2024). "IRF7 is also expressed by plasmacytoid dendritic cells and is overexpressed in psoriasis." (PMID 33812333, 2021). "Therefore, we identified novel function of Zdhhc2 in controlling inflammatory response in psoriasis in mice and we also confirmed that crucial role of Zdhhc2 in pDCs by regulating IRF7 activity and production of the critical cytokine." (PMID 33488612, 2020). "As a central transcription factor in IFN-I signaling, IRF7 is broadly activated in diseases such as SLE, psoriasis, and atopic dermatitis, enhancing local IFN responses and driving chronic inflammation." (PMID 41383611, 2025). "In psoriasis, IRF3 and IRF7 are similarly overexpressed in lesional skin, driving IFN-α production and exacerbating local inflammation." (PMID 41383611, 2025). "Interestingly, the imiquimod induced psoriasis model in knocking down Tet2 mice displayed decreased skin lesions with a reduced expression of biomarkers genes, such as S100A7, IL7R, and IRF7." (PMID 34769338, 2021). "In addition, gene methylation profiles of psoriasis patients indicate that genes belonging to the IL17 signaling pathway, Staphylococcus aureus infection, interferons, and immune cells migration displayed abnormal methylation, including IRF7, IL7R, and CXCL1." (PMID 34769338, 2021).
systemic sclerosis (6 papers, 2021 to 2024). A chronic disorder, possibly autoimmune, marked by excessive production of collagen which results in hardening and thickening of body tissues. "IRF7 activation has been found to aggravate autoimmune pancreatitis, inflammatory progression, and fibrosis in systemic sclerosis." (PMID 38671352, 2024). "Rezaei R analyzed the methylation status of CpG sites of the IRF7 promoter in peripheral blood mononuclear cells (PBMCs) of systemic sclerosis (SSc) patients and found that hypomethylated CpG2 was associated with increased disease risk." (PMID 37638030, 2023). "IRF7 has been shown to be involved in various diseases, including hepatitis C infection, systemic sclerosis, and pulmonary hypertension." (PMID 35500231, 2022). "In systemic sclerosis, silencing IRF7 alleviates dermal fibrosis and inflammatory responses." (PMID 36336986, 2023). "The interferon regulatory factor 7 (IRF7), a member of the IRF family of transcription factors, plays a major role in the regulation of numerous aspects of an immune response and has increasingly been surveyed to determine the aetiology and pathogenesis of systemic sclerosis (SSc)." (PMID 39886279, 2024).
acute myeloid leukemia (5 papers, 2021 to 2023). Acute myeloid leukemia (AML) is a group of neoplasms arising from precursor cells committed to the myeloid cell-line differentiation. "Here we used MLL-AF9-induced acute myeloid leukemia (AML) mouse models with IRF7 knockout or overexpression and xenograft mouse models to explore the intrinsic effects of IRF7 in AML." (PMID 35256780, 2022). "To further elucidate the disordered regulation of immune responses and mitochondrial OXPHOS in Mono.M7.prog, we checked the role of IRF7 with IRF7‐knockout and MLL‐AF9‐induced acute myeloid leukemia (AML) mouse models." (PMID 37750090, 2023).
Arthritis (5 papers, 2021 to 2023). Inflammation of a joint. "In M2-polarizing conditions, a pro-M1 and pro-angiogenic upstream regulator Irf3, and the pro-M1 pro-arthritis upstream regulator Irf7, and NF-κB were all predicted to be activated by 65–79*SE, and reciprocally inhibited by 65–79*PE." (PMID 33510427, 2021). "Irf7-deficient B6 mice with K/B×N serum transfer arthritis had increased arthritis severity, with augmented systemic and local proinflammatory cytokines, indicating an overall anti-inflammatory role of IRF7 (ascribed to its regulation of IFN production and cytokine gene expression)." (PMID 36591261, 2022). "IRF7 has an anti-inflammatory function in arthritis via the initiating of immunity." (PMID 33748207, 2021). "In an arthritis model, IRF7 deficiency exacerbates the clinical severity, proinflammatory cytokines are increased, anti-inflammatory cytokine IFN-β is decreased, and IRF7 regulates the expression of IFN-β in murine macrophages but not in stromal fibroblast-like synoviocytes." (PMID 37638030, 2023).
co-infection (5 papers, 2017 to 2025). "Another study found that PDCoV and PEDV co-infection regulated pro-inflammatory cytokines through the TRAF6-mediated canonical NF-κB and IRF7 signaling pathways, leading to enhanced viral evasion of the mucosal innate immune response." (PMID 40943649, 2025). "Meanwhile, single-PDCoV infection and PDCoV/PEDV co-infection regulate proinflammatory and regulatory cytokines through TRAF6-mediated canonical NF-κB and IRF7 signaling pathways through TLRs." (PMID 36376395, 2022). "There is evidence indicating that the antiviral response to PRRSV and the IBV/PRRSV co-infection uses a combination of ISGs and IRFs such as IRF1, IRF4, and IRF7 to drive the host response." (PMID 33187194, 2020). "In addition, IRF7 was also up-regulated by single-PDCoV and -PEDV infection by 5 DPI, while PDCoV/PEDV co-infection induced the same regulatory effect by 3 DPI." (PMID 36376395, 2022). "In the case of the co-infection group, expression of both IRF1 and IRF7 may be the result of the viral sequence and etiology." (PMID 33187194, 2020). "The IBV/PRRSV group expressed upregulation of one additional interferon regulatory factor, IRF7, but had no IRF expression at 7 dpi despite the co-infection." (PMID 33187194, 2020).
colitis (5 papers, 2021 to 2025). Inflammation of the colon. "Their mechanistic studies using IRF7-deficient murine models demonstrated exacerbated susceptibility to DSS-induced colitis, characterized by heightened systemic and colonic pro-inflammatory cytokine profiles." (PMID 40506039, 2025). "In the mouse model of dextran sodium sulfate-induced colitis, knockout of the interferon regulatory factor Irf7 or the interferon-λ receptor (Ifnlr1) gene increased susceptibility to colitis; administration of interferon-λ2 reversed the effect of Irf7 knockout." (PMID 40996888, 2025). "The phosphorylation of STING and activation of downstream transcription factors, including interferon regulatory factor 3 (IRF3), nuclear factor kappa-B (NF-κB), and IRF7, were all significantly elevated in colitis." (PMID 39113810, 2024). "IRF3 and IRF7 are important for induction of IFN-λ, IFN-α/β, and ISGs; experiments in IRF3/IRF7 double knockout mice with DSS colitis showed greater tissue inflammation relative to controls, suggesting a mucosal protective effect of IFN responses in colonic tissues." (PMID 34712246, 2021). "Notably, we observed a population of Tregs with high expression of ISGs (e.g., Irf7, Irf9, Isg15) from mesenteric lymph nodes (MLNs) during dinitrobenzenesulfonic acid (DNBS)–induced colitis." (PMID 38085267, 2024).
encephalitis (5 papers, 2020 to 2025). An acute inflammatory process affecting the brain parenchyma. "This study reports an infant with recurrent HSV-1 disease complicated by encephalitis associated with deleterious variants in the IRF7 and UNC93B1 genes." (PMID 37097753, 2023). "In an acute HSV-encephalitis model, an IRF7 deficiency was associated with reduced IFN responses, increased viral titer in the brain, and high mortality." (PMID 34389779, 2021). "The finding of AAN-I-IFN in patients with WNV encephalitis or TBE, in turn, also suggests that the extremely rare cases of WNV encephalitis or TBE in patients with deleterious mutations of GATA2 or IRF7 are probably also due to impaired type I IFN antiviral immunity." (PMID 41608126, 2025). "Although disease progression was faster in SARS-CoV-2 infected mice, infection with both viruses resulted in neuronal infection and encephalitis with increased expression of Interferon-stimulated Irf7, Bst2, Ifi294, as well as CxCL10, CCL5, CLC2, and LILRB4, and both models were uniformly lethal." (PMID 35967447, 2022).